RNU2-39P (RNA, U2 small nuclear 39, pseudogene)
Gene: Small nuclear RNA gene on chromosome 2 (72,721,806 to 72,722,003, forward strand). Ensembl gene ENSG00000222536.
Homologues: Orthologues: chimpanzee U2 (94% identical), macaque U2 (94% identical), dog U2 (73% identical), dog U2 (72% identical), guinea pig U2 (66% identical), pig U2 (65% identical), mouse Gm23206 (59% identical), rat LOC120098016 (59% identical). Paralogues in human: U2 (79% identical), U2 (78% identical), RNU2-43P (77% identical), RNU2-4P (77% identical), RNU2-61P (77% identical), RNU2-64P (77% identical), RNU2-68P (77% identical), RNU2-2 (76% identical), RNU2-3P (76% identical), RNU2-59P (76% identical), RNU2-6P (75% identical), RNU2-14P (74% identical), and 67 more.